LEP (leptin)
Diseases named in the same sentence as LEP in open-access papers (continued):
Sharing a sentence is not in itself a finding about the gene and the disease.
type 2 diabetes (continued). "ob/ob Mice are well suited for studies on the interaction between leptin and insulin, and for studies on initial aspects of metabolic disturbances leading to type-2 diabetes." (PMID 17619751, 2007). "In addition, our results indicated that obese individuals with type 2 diabetes exhibited elevated HbA1c, leptin, total cholesterol, HDL, LDL, and fasting plasma glucose compared to non-obese individuals with the same condition." (PMID 41239622, 2025). "The authors concluded that excess pancreatic fat is largely stored within adipocytes and that secreted products from these cells, including adipokines and leptin, may contribute to islet dysfunction in type 2 diabetes." (PMID 40991018, 2025). "Additionally, the combination of dapagliflozin and metformin treatment significantly reduced PRAT layers in obese patients with type 2 diabetes, accompanied by reductions in plasma leptin, C-reactive protein, and urinary microalbumin levels." (PMID 40487756, 2025). "Furthermore, serum ANRIL levels were elevated in individuals with type 2 diabetes and strongly correlated with pro-inflammatory markers leptin and hs-CRP (both p < 0.001), in line with findings from studies on diabetic and cancer patients." (PMID 40940402, 2025). "Based on previous studies, the authors hypothesize that intermittent fasting has a statistically significant effect on serum leptin in obese type 2 diabetic patients with a medium effect size (dz = 0.5)." (PMID 38172970, 2024). "Sáinz (2015) suggests that anti-inflammatory drugs or bioactive food components could help overcome leptin resistance, while Salazar (2019) underscores the importance of addressing leptin resistance in the context of type 2 diabetes." (PMID 39767708, 2024). "We then hypothesized that combined IP6 and inositol supplementation might promote insulin sensitivity in type 2 diabetic rats by increasing leptin levels in the blood." (PMID 37371552, 2023). "In our study, the leptin level was already higher among patients with type 2 diabetes even with normal BMI (Group D), was significantly higher in obese non-diabetic patients (Group O), and was the highest in obese patients with type 2 diabetes (Group OD) when compared to the control group." (PMID 36901837, 2023). "Moreover, plasma leptin levels are increased in obese type 2 diabetes patients, significantly post-LSG, which indicates the potential of LSG in modifying the conditions of type 2 diabetes by reducing the level of leptin." (PMID 36998473, 2023). "In addition to the induction of insulin resistance, Type II diabetes can also impair other metabolic hormones such as leptin and adiponectin as well as reduce steroidogenesis and testosterone levels." (PMID 37497106, 2023). "Type 2 diabetes (T2D) can exacerbate periodontitis by influencing leptin." (PMID 38111655, 2023). "Evidence indicate that inflammation and, in particular, high levels of TNF-α, IL-β and IL-6 are factors involved in the development of type-1 diabetes, and TNF- α, IL-1, IL-6, IL-10, leptin, and adiponectin are the factors involved in the development of type-2 diabetes." (PMID 36011116, 2022). "Curcumin could be used to avoid colorectal cancer (CRC) in diabetics with type 2 diabetes by lowering leptin blood levels and increasing adiponectin levels." (PMID 35401176, 2022). "In addition, leptin is a potential biomarker of Crohn’s disease, ulcerative colitis and ischemic heart disease in type 2 diabetes." (PMID 35884340, 2022). "Moreover, in patients with type II diabetes, the circulating leptin concentrations tend to decrease following exercise." (PMID 36404859, 2022). "Genetic leptin deficiency or lack of functional leptin receptor has been shown to alter brain proteins and neuronal functions of mice and induce morbid obesity and type 2 diabetes which can be reversed by leptin replacement therapy." (PMID 34356668, 2021).
type 2 diabetes (continued). "Similarly, leptin therapy only produces modest effects on insulin sensitivity in type 2 diabetes due to leptin resistance." (PMID 33935782, 2021). "The study further advances our knowledge of the downstream signaling events that may be targeted to restore insulin secretion regulation in β-cells defective in leptin signaling, such as those from obese individuals with type 2 diabetes." (PMID 33617875, 2021). "A major strength of this review is the inclusion of clinical studies involving diverse patient cohorts (CAVD, MI, SLE, Type 2 diabetes) presenting elevated circulating leptin levels as well as animal studies ranging from global to cell-specific transgenic murine models." (PMID 34064112, 2021). "Sex hormones such as sex hormone-binding globulin have been identified to have sex-dependent effects on leptin and Type 2 diabetes, and might explain the sex-dependent effects of leptin that were observed in this study." (PMID 32374776, 2020). "Finally, exercise can decrease leptin resistance, a condition characteristic for type 2 diabetes and contributing to hyperleptinaemia and thus lead to decrease in leptin levels." (PMID 32652863, 2020). "The main findings of this study are that the 4‐months of regular interval walking training resulted in a statistically significant decrease in albuminuria and leptin/adiponectin ratio, as well as moderate improvement in HbA1c level in patients with type 2 diabetes." (PMID 32652863, 2020). "Geniposide, an active component of Fructus Gardeniae, could enhance leptin signaling to attenuate the level of Aβ1–42 in Alzheimer's disease and activate PPARγ to reduce the blood glucose level in type 2 diabetes." (PMID 33178326, 2020). "Another enriched pathway ‘Leptin signalling pathway’ also links lipodystrophy with type 2 diabetes." (PMID 32491965, 2020). "Our finding of increased risk of type 2 diabetes with increased levels of leptin observed among abdominally non-obese participants adds weight to the “leptin resistance’ phenomenon in the context of a large population sample." (PMID 32131811, 2020). "In contrast to these studies, our investigation showed that BMI did not change the association between leptin and type 2 diabetes, but that abdominal obesity did." (PMID 32131811, 2020). "Using a discovery replication strategy and large-scale proteomics data, we identified consistent positive associations between leptin and A-FABP in two independent cohorts of patients with type 2 diabetes, an association which appeared stronger in men than in women." (PMID 32753620, 2020). "Thus, the aim of this study was to investigate the effects of personalized interval walking training delivered through smart mobile devices on albuminuria and leptin/adiponectin ratio in patients with type 2 diabetes." (PMID 32652863, 2020). "Furthermore, n-3 PUFA supplementation in type 2 diabetes patients brought leptin levels down and increased the adiponectin level, which resulted in positive effects on lipid profile, insulin, and glycosylated hemoglobin." (PMID 32059381, 2020). "Leptin has been reported to reduce hyperglycaemia in rodent models of type 1 diabetes and has recently been shown to normalise fasting plasma glucose concentrations in a rodent model of polygenic obesity and type 2 diabetes." (PMID 29085991, 2018). "However, a significant decrease in blood leptin concentration was noted 24 h after a single endurance exercise in women and men with type 2 diabetes." (PMID 30618797, 2018). "However, in the state of leptin resistance, which is often found in type 2 diabetes, leptin cannot exert its effects, making these individuals resistant to the weight-reducing effects, even in the presence of hyperleptinemia." (PMID 30380802, 2018). "Dysregulation of SOCS-3 signaling may contribute to the development of type 2 diabetes in obese individuals whose β-cells become resistant to leptin signaling, leading to chronic insulin hypersecretion that eventually causes β-cell failure." (PMID 27242781, 2016).
type 2 diabetes (continued). "Thus, during the development of the type 2 diabetes, increasing serum concentrations of insulin and leptin, decreasing plasma ghrelin, and declining ghrelin’s stimulation on hypothalamic ARC NPY neurons were observed from the control group to the DIO8W group." (PMID 27867820, 2016). "Twenty-four-hour total ghrelin and overnight fasting leptin concentrations were determined in males with type 2 diabetes when ingesting a standard, mixed meal diet (control), followed by a carbohydrate-free diet for 72 h or were starved for 72 h, using a crossover design." (PMID 27453716, 2016). "Thus far, no reports examining the associations among adiposity, plasma leptin, and HRV in patients with type 2 diabetes have been presented." (PMID 26338087, 2015). "Consistent with our findings in mice, a relative leptin deficiency has been associated with lack of remission of type 2 diabetes after RYGB in patients exhibiting the expected post-surgical weight loss." (PMID 26445459, 2015). "Interestingly, presence of higher leptin levels especially in obese subjects makes them even more resistance to insulin-like effects thus mediating type 2 diabetes in obese subjects." (PMID 25897417, 2015). "Leptin resistance impairs peripheral glucose homeostasis by decreasing the hypothalamic response to insulin that may lead to the onset of type 2 diabetes." (PMID 25587271, 2014). "The decreased leptin levels following the large amount of nutrients on the Mediterranean-lunch are corroborated by earlier finding that longer cooking-time to enhance nutrient availability reduced leptin levels postprandially in type 2 diabetes." (PMID 24312178, 2013). "In conclusion, atorvastatin treatment may have several effects on the interaction between leptin and adiponectin, and on clinical parameters in patients with type II diabetes." (PMID 24255692, 2013). "Thus, we found that only in subjects with type 2 diabetes, serum leptin levels depend on HOMA-IR calculated using insulin and glucose concentrations." (PMID 23853613, 2013). "The possible trigger for type 2 diabetes might be related to leptin resistance, which further inhibits the liver AMPK-ACC signaling pathway and causes liver and systemic metabolic disorders." (PMID 24455748, 2013). "Interestingly, a number of anti-diabetic compounds such as thioglitazone, pioglitazone, rosiglitazone and metformin used to treat type-2-diabetes work through inhibition of leptin expression." (PMID 23544120, 2013). "Our results suggested that administration of Lr263 could prevent the development of type 2 diabetes by normalizing serum levels of glucose, insulin, C-peptide and leptin." (PMID 23590862, 2013). "Moreover, leptin relationships with metabolic alterations and type-2 diabetes are strongly affected by the genetic type, the breed, both at infant and adult stages." (PMID 24205230, 2013). "The ob/ob mouse model of insulin resistance is robust, well characterized and used extensively to study type 2 diabetes and its therapies; however, it is worthy of note that it is a monogenic paradigm of leptin deletion, whereas type 2 diabetes mellitus is a polygenic disorder." (PMID 19968882, 2009). "Our previous study, which examined the effects of combined IP6 and inositol supplementation in type 2 diabetic rats, indicates that the notable rise in serum leptin levels could potentially contribute to the reduction of food intake and prevention of body weight gain." (PMID 37371552, 2023). "Therefore, leptin and insulin affect each other in the production mechanism, and their interaction participates in the genesis and development of many diseases such as type 2 diabetes." (PMID 33833859, 2021). "Furthermore, relieving ER stress with chemical chaperones, i.e., agents that have the ability to increase ER folding machinery, increases insulin sensitivity and reverses type 2 diabetes in adult ob/ob mice while showing improved leptin sensitivity in adult obese mice fed a high-fat diet (HFD)." (PMID 32163401, 2020).
type 2 diabetes (continued). "Of note, increased circulating leptin levels have also been observed in obese patients and patients with type 2 diabetes mellitus (T2DM)." (PMID 33203192, 2020). "Similarly, among Japanese Americans, increased baseline leptin levels were associated with increased risk of developing type 2 diabetes in men but not in women." (PMID 32131811, 2020). "Nevertheless, differences by sex in body fat composition—with women generally having a higher body fat percentage and, thus, higher leptin levels—may explain why the association between leptin and type 2 diabetes appears in men but not in women." (PMID 32131811, 2020). "Thus defect in glucose sensing, as seen in type 2 diabetes could be responsible for the lower leptin production, suggesting a signalling crosstalk in glucose regulation." (PMID 29422086, 2018). "However, in type 2 diabetes, leptin levels are generally higher independently of body fat mass." (PMID 30380802, 2018). "However, leptin treatment in obese human participants with type 2 diabetes did not have any weight loss effects and only marginally reduced blood glucose." (PMID 30094465, 2018). "With regard to epidemiological evidence, high concentrations of leptin, resistin, visfatin, and PAI-1 have been associated with an increased risk of type 2 diabetes, whereas high adiponectin concentrations have been associated with a decreased risk of obesity and type 2 diabetes." (PMID 28552966, 2017). "Thus, LEP may involve in the etiology of obesity, type 2 diabetes (T2DM) and pathophysiology of carcinoma." (PMID 29312594, 2017). "This might support the notion that patients with type 2 diabetes suffer from leptin resistance." (PMID 27216013, 2016). "This study aimed to investigate the changes of hypothalamic NPY levels and the main hormones that regulate the synthesis and release of hypothalamic NPY, including insulin, leptin, and ghrelin, and may provide additional insights into the study of the pathogenesis of type 2 diabetes." (PMID 27867820, 2016). "Increased plasma leptin levels found in obese individuals (particularly in those with visceral obesity) a condition which is similar to the increases of this adipokine found in our rats, have been positively correlated with endothelial dysfunction, IR, oxidative stress, and type-2 diabetes." (PMID 27792195, 2016). "Thus, reduced bone strength observed with type 2 diabetes may be related to the role leptin plays in the regulation of bone mass." (PMID 25789256, 2015). "Moreover, we speculated that the reduction serum leptin levels in type 2 diabetes and even lower levels in subjects with poorly controlled diabetes was likely due to male gender, insulin deficiency, and defect of β-cell function." (PMID 23853613, 2013). "In the present study, leptin was significantly associated with type 2 diabetes risk after adjusting for age, gender and BMI, but this association was no longer significant after adjusting for the type 2 diabetes risk score." (PMID 23251619, 2012). "However, the evidence relating leptin to SNS in type 2 diabetes is less clear." (PMID 22413919, 2012). "Finally, going a step further by searching the 4-dimensional subnetwork, the researcher discovers that the interaction among aspirin, HMG-CoA reductase, leptin and type 2 diabetes with interaction level l4 = 0.7178 is in fact the most promising interaction for research." (PMID 22369514, 2011). "However, rather than leptin deficient, obese persons often have hyperleptinemia specified as “selective leptin resistance” associated with MetS, type 2 diabetes and cardiovascular disease (CVD)." (PMID 21347230, 2011). "Adipokines such as leptin, resistin and adiponectin are currently investigated as potential future drug targets in type 2 diabetes mellitus (T2D), lipid metabolism, endothelial dysfunction and inflammatory diseases in general." (PMID 17295929, 2007).
type 2 diabetes (continued). "It is reported that melatonin (MLT) plays a protective role against type 2 diabetes mellitus (T2DM) through regulation of glucose metabolism in animals and patients via changes in insulin secretion and leptin production." (PMID 39564526, 2024). "In patients with type 2 diabetes, HDL-C is positively correlated with serum adiponectin and negatively correlated with leptin." (PMID 39421410, 2024). "An important observation in our study is that SIT acts as effectively as metformin to normalize the serum adipokine levels including leptin, resistin, adiponectin, TNF-α, IL-6, SREBP-1c and PPARγ in HFD and sucrose induced type 2 diabetic rats." (PMID 33917607, 2021). "The serum leptin and resistin levels were drastically increased and the serum adiponectin levels were significantly reduced in HFD and sucrose induced type 2 diabetic rats when compared to control rats." (PMID 33917607, 2021). "This study aimed to investigate the effects of 4 weeks of HFD consumption with a low dose of STZ, 12 weeks of AET (5 days/week) and RET (3 days/week), and 4 weeks of de-training on leptin, TNF-α and other metabolic parameters in type 2 diabetic rats." (PMID 34039404, 2021). "We observed a high correlation between BW of type 2 diabetic rats and FBG, TG, LDL-C, leptin, insulin, and TNF-α." (PMID 34039404, 2021). "We aimed to discover novel associations between leptin and circulating proteins which could link leptin to the development of cardiovascular disease in patients with type 2 diabetes (T2DM)." (PMID 32753620, 2020). "In this regard, when co-administered with leptin, liraglutide (a GLP-1 receptor agonist approved for the treatment of type 2 diabetes) presumably enhanced pSTAT3 after the inhibition of PTP1B." (PMID 32069871, 2020). "IL-6, leptin, and RBP4 levels were higher in those who developed type 2 diabetes than in the other groups." (PMID 31690939, 2020). "In this study, the direct association between leptin and incident type 2 diabetes observed among abdominally non-obese participants supports previous findings that about 40% of the variation in leptin in obese subjects could be explained by peripheral fat distribution." (PMID 32131811, 2020). "In Sawano cells and normal HEEs, a decrease of LSR induced by leptin and an increase of LSR induced by adiponectin and the drugs for type 2 diabetes metformin and berberine were observed via distinct signaling pathways including JAK2/STAT." (PMID 27036040, 2016). "It has been reported that adiponectin and leptin levels, which are both modulated by PPAR α/γ dual agonists, are also influenced by type 2 diabetes." (PMID 24244369, 2013). "In agreement with our previous study, decreased leptin expression and increased expression of the leptin receptor were also found in the high fat diet plus low dose STZ-induced type 2 diabetic rats, 24–36 hours after chronic exercise." (PMID 24455748, 2013). "Studies regarding the relationship between leptin and HRV in type 2 diabetes are rare and have been inconclusive." (PMID 22413919, 2012). "Participants who developed type 2 diabetes during follow-up had significantly higher levels of IL-6, hs-CRP, leptin and γGT, and lower levels of adiponectin than participants who remained free from type 2 diabetes." (PMID 23251619, 2012). "On univariate analysis, participants who developed type 2 diabetes had significantly higher baseline levels of IL-6, CRP, leptin and γGT, and lower levels of adiponectin than participants who remained free of type 2 diabetes." (PMID 23251619, 2012). "In this paper, recent findings regarding the effects of cytokines including IL-1β, IFN-γ, TNF-α, leptin, resistin, adiponectin, visfatin, and PANDER on pancreatic β-cell dysfunction and type 2 diabetes will be summarized and discussed." (PMID 21113299, 2010).